PCSK9 (proprotein convertase subtilisin/kexin type 9)
Diseases named in the same sentence as PCSK9 in open-access papers (continued):
Sharing a sentence is not in itself a finding about the gene and the disease.
tumor (145 papers, 2010 to 2025). "High expression of PCSK9 in tumor tissues is associated with reduced lymphocyte infiltration and poorer outcomes in patients undergoing therapy with an ICI." (PMID 40507315, 2025). "Research studies have demonstrated that elevated PCSK9 expression is associated with boosted PC cell proliferation, invasion, and migration, proposing its potential mitogenic contribution to tumor progression." (PMID 40362754, 2025). "PCSK9 has been implicated in tumor progression through its role in lipid metabolism, immune evasion, and inflammatory signaling." (PMID 40364115, 2025). "The V474I variant represents a gain-of-function mutation that enhances the activity of PCSK9, with profound implications for tumor biology." (PMID 39872986, 2025). "PCSK9 deficiency also increased the expression of MHC-I on the surface of tumor cells, exposing them to the immune defenses and allowing greater intra-tumoral cytotoxic T cell infiltration." (PMID 38672532, 2024). "Firstly, we found that PCSK9 expression was aberrantly elevated in different tumors and that high PCSK9 expression was associated with poor prognosis in most tumor types, although there are exceptions, such as BRCA and UCEC." (PMID 38600469, 2024). "Recent studies have demonstrated a close association between PCSK9 expression and tumor progression." (PMID 38617549, 2024). "Inhibiting PCSK9 caused a significant increase in tumor cell surface MHC-I expression, which promoted robust intra-tumoral infiltration of cytotoxic T-cells." (PMID 38600469, 2024). "Taking BLCA as an example, we found that abnormal expression of PCSK9 was associated with tumor invasion characteristics, cell hypoxia manifestations, and EMT-related markers." (PMID 37860186, 2023). "The gain-of-function (GOF) PCSK9 natural variant D374Y enhanced B16 cell-derived tumor growth compared to PCSK9 along with elevations of lipid accumulation; both events were significantly hindered by the loss-of-function (LOF) mutant Q152H." (PMID 36588164, 2023). "At the metabolic level, PCSK9 deficiency was capable of inducing oxidative phosphorylation, glycolysis and consumption of glutamine of tumor cells depending on the available nutritional resources." (PMID 36612001, 2022). "After that, we associated PCSK9 expression with clinicopathological data from the patients and found that PCSK9 expression was associated with advanced pathological grade of tumor." (PMID 36242053, 2022). "Beyond its critical role in maintaining lipid homeostasis, PCSK9 is implicated in various signaling pathways, including antiviral activity, apoptosis and, more recently, anti-tumor immune responses, as well as anti-oxidative housekeeping activities." (PMID 36552895, 2022). "PCSK9 inhibition, either through genetic deletion or PCSK9 antibodies, caused a significant increase in tumor cell surface major histocompatibility protein class I (MHC I) expression, which promoted robust intratumoral infiltration of cytotoxic T-cells." (PMID 34504788, 2021). "The expression of PCSK9 in tumor tissues of HCC patients was associated with large tumor size (p = 0.001) and microvascular invasion (p = 0.036)." (PMID 33789749, 2021). "In this study, we explored the molecular mechanism underlying the tumor promotion of PCSK9 in GC, which, to our knowledge, represented a pioneering comprehensive analysis of PCSK9 in GC." (PMID 33489919, 2020). "In this case, the role of PCSK9 andMBTPS1 in the pathological process is probably associated withthe involvement of the protein products of these genes in lipid metabolismand/or immune response evasion by tumor cells." (PMID 40264581, 2025).
tumor (continued). "The underlying mechanism might be related to the inhibition of tumor cell apoptosis by high expression of PCSK9." (PMID 39736777, 2024). "Additionally, several studies on cholesterol regulation in tumor sites have been proposed to be due to the corresponding association between PCSK9 and oncogenesis." (PMID 37860186, 2023). "The PCSK9 protein distributed in tumor tissue may have a more direct impact on the efficacy of ICIs, but no research was conducted discussing the association between efficacy and PCSK9 expression in tumor tissue in advanced NSCLC." (PMID 37025995, 2023). "On the contrary, current research has shown that PCSK9 deficiency inhibits tumor growth." (PMID 38093957, 2023). "Consequently, studies of the underlying mechanisms of the combination of mTOR and PCSK9 inhibitors in tumor treatment remain to be conducted in the future." (PMID 37896137, 2023). "Proprotein convertase subtilisin/kexin type 9 (PCSK9) is the ninth member of the proprotein convertase family that regulates lipoprotein homeostasis and altered PCSK9 expression was reportedly associated with tumor development and progression." (PMID 36242053, 2022). "This hypothesis was corroborated by data showing that long-term survivors of the first inoculation with PCSK9-deficient tumor cells developed anti-tumor immune memory, as shown by rejection of a second inoculation with wild-type tumor cells." (PMID 33677469, 2021). "Additionally, PCSK9 expression is positively associated with apoptosis in vascular endothelial cells, tumor cells, and neurons suggesting a detrimental role for PCSK9 on endothelial repair and vasculogenesis." (PMID 31366894, 2019). "In addition to its crucial role in maintaining lipid homeostasis, PCSK9 is also associated with various signaling pathways, such as enhancing viral activity, participating in cell apoptosis, and contributing to the anti-tumor immune response." (PMID 38027179, 2023). "In Fh1 knockout tumor mouse models, the combination of PCSK9 inhibitors and PD‐1 antibodies significantly improved the therapeutic effect of PD‐1." (PMID 40145543, 2025). "By suppressing LRP1 and enhancing proliferative competence, PCSK9 orchestrates a complex program that enables tumor cells to overcome the barriers to metastasis." (PMID 39872986, 2025). "Through in vitro co‐culture and tumor mouse models, the immune‐modulatory effects of PCSK9 inhibition were evaluated." (PMID 40145543, 2025). "Clinically approved PCSK9 neutralizing antibodies (100 μg intraperitoneally) have been shown to act synergistically with anti-PD1 therapy in suppressing tumor growth in mouse cancer models." (PMID 40270603, 2025). "Targeted inhibition using the small molecule PF-846 suppresses PCSK9 expression and significantly reduces tumour proliferation and metastasis in vitro and in vivo." (PMID 41008547, 2025). "The results revealed that the IHC scores of PCSK9 in tumor tissues were significantly higher than those in the adjacent tissues, increasing by 2.48‐fold." (PMID 40192514, 2025). "The pro-inflammatory effects of PCSK9 in neoplasm environments have been briefly demonstrated before." (PMID 40872487, 2025). "The down-regulation of preprotein convertase Bacillus subtilis protease/kexin type 9 (PCSK9) augments tumor infiltration by cytotoxic T-cells, improves the effectiveness of anti-PD-1 therapies, and is pivotal in the anti-tumor immune response." (PMID 40066091, 2025).
tumor (continued). "Further complicating the tumor microenvironment is PCSK9’s ability to alter macrophage polarization, thereby creating conditions favorable for tumor growth." (PMID 41458606, 2025). "The study revealed that PCSK9 enhances the proliferative competence of disseminated tumor cells, thereby facilitating their progression to macroscopic metastases." (PMID 39872986, 2025). "To pursue an effective immunotherapy for MSS CRC tumor, we evaluated the effect of PCSK9 inhibition on MSS CRC tumor progression." (PMID 40125618, 2025). "The presumed purpose behind this PCSK9 response would be to re‐establish circulating levels of LDL consumed by tumor cells." (PMID 39888285, 2025). "Gene knockdown and overexpression experiments further revealed the importance of PCSK9 in tumor growth and metastasis." (PMID 40192514, 2025). "Gene knockout or PCSK9 antibody inhibition increases the expression of MHC‐I proteins on the tumor cell surface, promoting strong infiltration of cytotoxic T cells within tumors and enhancing the efficacy of anti‐PD1 therapies." (PMID 40145543, 2025). "Our findings establish a mechanistic link between amino acid metabolism and cholesterol metabolism in the tumor microenvironment where tumor cells sense methionine to deploy PCSK9 expression." (PMID 40125618, 2025). "Our study uniquely shows that PCSK9 promotes tumor progression by directly regulating E-cadherin expression, enriching current research and elucidating its broader role in tumor biology." (PMID 40328788, 2025). "Nevertheless, knockdown of the immunometabolism checkpoint PCSK9 abolished the disparity in tumor progression induced by DMR." (PMID 40125618, 2025). "While most studies focus on PCSK9 in tumor cells, its role in the tumor microenvironment remains largely unexplored." (PMID 40563628, 2025). "This distinction underscores the specific role of PCSK9 in modulating tumor biology, which is separate from its function in lipid metabolism." (PMID 39872986, 2025). "PD-1 blockade is a widely used immunotherapy strategy in neoplasms, and a gene mapping analysis has found the upregulation of PCSK9 in neoplasm cells during the anti-PD-1 process." (PMID 40872487, 2025). "Knockdown of PCSK9 greatly decreases the tumorigenic and metastatic potential of 4–11 cells, whereas overexpression of PCSK9 significantly enhances tumor maliganancy." (PMID 40192514, 2025). "DECP, by targeting PCSK9, inhibited PCSK9 activity, increasing the proportion of mature DCs, tumor‐infiltrating CD8+ T cells, and natural killer cells in HCC, while depleting Foxp3+ regulatory T cells." (PMID 40145543, 2025). "In contrast, among patients with PTC, increased PCSK9 expression was closely linked to higher pT stage, pN grade, and distant metastasis, underscoring PCSK9’s role in driving tumor progression in TC." (PMID 40328788, 2025). "They found that ARBU inhibited cholesterol synthesis in the tumor microenvironment via the PCSK9/LDL‐R signaling pathway, blocking M2 macrophage polarization, promoting tumor cell apoptosis, and inhibiting tumor cell proliferation and migration." (PMID 40145543, 2025). "PCSK9 has been proposed as a multifunctional regulator of tumour progression and metastasis through its ability to reprogram the tumour microenvironment and intracellular signalling networks." (PMID 41008547, 2025). "By inhibiting PCSK9, the inflammatory process contributing to neoplasm occurrence and progression would be subsequently compromised." (PMID 40872487, 2025). "Inhibition of PCSK9 enhances the expression of major histocompatibility complex class I (MHC I) proteins on tumor cell surfaces, facilitating significant intratumoral infiltration of cytotoxic T lymphocytes." (PMID 40354375, 2025). "We further investigated the effects of overexpressing PCSK9 on tumor growth and metastasis in 231‐GFP cells in vivo." (PMID 40192514, 2025).
tumor (continued). "A recent study showed that PCSK9 is overexpressed in colon cancer tissues and correlated with a worse tumor pathological grade." (PMID 40362754, 2025). "It has been shown that tumor-derived signals upregulate PCSK9 expression, supporting vascular co-option—a mechanism allowing tumor cells to reorganize independently of angiogenesis." (PMID 40563628, 2025). "Recent studies have demonstrated that PCSK9 can regulate immune responses through interactions with immune cells and components of the tumor microenvironment." (PMID 40354375, 2025). "Gene silencing of PCSK9 in model systems attenuates this phosphorylation cascade and impairs tumour cell motility." (PMID 41008547, 2025). "In pediatric cancers such as medulloblastoma, PCSK9 acts as a tumor-specific neoantigen, triggering T-cell responses and presenting potential as an immunotherapy target." (PMID 40370434, 2025). "Corroborating their known pleiotropic effects, preclinical studies have demonstrated that PCSK9 inhibition synergistically enhances immunotherapy’s anti-tumor effects through LDL-receptor-independent pathways." (PMID 39268545, 2024). "Previous studies have demonstrated that the deletion or pharmacological inhibition of PCSK9 in tumor cells can enhance the anti-tumor activity of CD8+ T cells, subsequently impeding tumor progression." (PMID 38398104, 2024). "Pharmacological inhibition of PCSK9 enhanced tumor-specific killing and downregulated PD-1 expression of AFP-specific TCR-T." (PMID 39113701, 2024). "In all four models, PCSK9-neutralizing antibodies synergistically inhibited tumor growth with anti-PD-1 therapy." (PMID 39736777, 2024). "In most tumor types, PCSK9 expression was negatively correlated with the immune, stomal, and ESTIMATE scores." (PMID 38600469, 2024). "And targeting PCSK9 also increases the expression of major histocompatibility protein class I (MHC-I) proteins on the tumor cell surface, promoting robust intratumoral infiltration of cytotoxic T cells." (PMID 38850359, 2024). "Then, we explored the anti-tumor activities of PCSK9 blockade and its regulatory effects on the TME in syngeneic mouse models." (PMID 38600469, 2024). "By combining a PCSK9 inhibitor with an immune checkpoint inhibitor, these trials hope to achieve synergistic effects of increasing tumor immunogenicity and overcoming PD-1/PD-L1-mediated immune suppression." (PMID 39324018, 2024). "Our findings not only enhance our understanding of the role of PCSK9 inhibitors in tumor therapy but also provide a theoretical basis for their clinical application." (PMID 38275613, 2024). "First, the optimal dose, timing, and duration of PCSK9 inhibition and anti-PD-1/PD-L1 immunotherapy need to be determined based on the tumor type, phase, and molecular characteristics." (PMID 39324018, 2024). "Specifically, PCSK9 can serve as a pivotal factor in the regulation of MHC-I recycling, T-cell receptor (TCR) recycling, and tumor-associated macrophages (TAMs)." (PMID 38185721, 2024). "In the context of colon cancer, a study has revealed that PCSK9 expression is upregulated in tumor cells and correlates with their invasiveness." (PMID 38473748, 2024). "Here, we explored the correlations of PCSK9 with anti-tumor immunity, including the immune score, immune cell infiltration, and the relationship with the expression level of immune checkpoints." (PMID 38600469, 2024). "After that, they combined the anti-PD-1 therapy with an anti-PCSK9 antibody and detected PD-1 blockade-induced Treg cells and tumor-infiltrating CD8+ T cells." (PMID 39324018, 2024).
tumor (continued). "Our findings displayed that the mRNA expression of PCSK9 was higher in tumor tissues than in normal tissues in LIHC and correlated with poorer OS." (PMID 38600469, 2024). "Apart from restraining tumor growth via the cholesterol depletion-mediated pathway, more studies have shown that PCSK9 inhibition can also potentiate the effects of PD-1/PD-L1 blockades, which suggests a novel approach for tumor treatment." (PMID 39324018, 2024). "Encouragingly, the inhibition of PCSK9 has also been shown to enhance the anti-tumor efficacy of T cells in melanoma and colorectal cancer." (PMID 39113701, 2024). "Clinically approved PCSK9-neutralizing antibodies synergize with anti-PD-1 therapy to inhibit tumor growth." (PMID 39402302, 2024). "Among the 39 TCGA tumor types and subtypes, the expression of PCSK9 in BRCA, BRCA-Luminal, and THCA was significantly positively correlated with the infiltration of B cells, CD8+ T cells, CD4+ T cells, macrophages, neutrophils, and DCs." (PMID 38600469, 2024). "Statistical analysis indicated a significant increase of PCSK9 expression in tumor tissues (t = 7.693, P < 0.01) compared to normal tissues." (PMID 39282119, 2024). "The inhibition of PCSK9 results in an augmented MHC-I expression on the tumor cell surface, thereby facilitating the infiltration of cytotoxic lymphocytes within the tumor microenvironment." (PMID 38473748, 2024). "The latest research developments highlight variances in PCSK9 expression levels observed between normal and tumor cells." (PMID 38822303, 2024). "Our results indicated that PCSK9 was highly expressed in most tumor types and was significantly correlated with late disease stage and poor prognosis." (PMID 38600469, 2024). "Our results suggested that PCSK9 inhibition is a promising combination therapy for MHC class-II restricted tumor vaccines." (PMID 38600469, 2024). "We systematically compared the mRNA expression levels of PCSK9 between normal tissues and tumor tissues across 33 tumor types in the TCGA cohort." (PMID 38600469, 2024). "More recently, research has shown that PCSK9 is involved in both anti-tumor immunity and immunological response." (PMID 39282119, 2024). "In line with expectations, we found that targeting PCSK9 enhanced the tumor response to anti-PD-1 immunotherapy." (PMID 39113701, 2024). "Then, we analyzed the correlation between the expression levels of PCSK9 and patient prognosis across multiple tumor types." (PMID 38600469, 2024). "They found that the inhibition of PCSK9 enhanced the tumor response to PD-1 inhibitors by promoting massive infiltration of CTLs within the tumor through a mechanism independent of the cholesterol regulatory function of PCSK9." (PMID 39736777, 2024). "All tumor cases were divided into the PCSK9 high-expression group and the PCSK9 low-expression group according to the expression level with a cutoff of 50% of PCSK9 expression." (PMID 38600469, 2024). "Recent findings suggest that inhibiting PCSK9 enhances the tumor’s response to immune checkpoint therapy, and both genetic and pharmacological reduction of PCSK9 can suppress tumor growth." (PMID 38822303, 2024). "Our in vivo experiments showed that the knockdown of FH affected the volume and magnitude of tumor regression after PD-1 immunotherapy and PCSK9 inhibition reversed the effect of immunotherapy." (PMID 38398104, 2024). "Our study comprehensively investigated the immunoregulatory role of PCSK9 in multiple tumor types and provided a theoretical basis for the application of PCSK9-targeted immunotherapy in tumor patients." (PMID 38600469, 2024). "PCSK9 inhibition can lower serum cholesterol levels and suppress tumor growth by modulating tumorigenic signaling pathways, ferroptosis, and the TME." (PMID 39324018, 2024). "Since serum cholesterol levels are closely related to tumor proliferation and development, the inhibition of PCSK9 can suppress tumor growth to a certain extent by lowering serum cholesterol levels." (PMID 39324018, 2024).